SETD2 (SET domain containing 2, histone lysine methyltransferase)
Diseases named in the same sentence as SETD2 in open-access papers (continued):
Sharing a sentence is not in itself a finding about the gene and the disease.
tumor (continued). "This lower expression is correlated with a poor prognosis and SETD2 overexpression in GC cell lines significantly inhibited cell proliferation, migration, and invasion hence reinforcing the hypothesized role of tumor suppressor of the SETD2 gene in GC." (PMID 39591760, 2025). "Thus, H3K36me3 deregulation drives oncogenesis and metastasis in cancers beyond RCC, suggesting that SETD2's tumor/metastasis suppressor function is conserved among different tissues and independent of mutations commonly linked to ccRCC like VHL and PBRM1." (PMID 37418588, 2024). "Genomic studies have revealed mutations in genes such as SETD2, CDKN2A, SMARCB1, and NF2, which may contribute to the tumor's aggressive phenotype." (PMID 39310439, 2024). "Since LF2 along with LF1 and LF5 levels were associated with patient overall survival, we generated Cox Proportional-Hazards models to evaluate how they compared to existing models of patient prognosis based on tumour stage, grade and somatic mutations (BAP1, SETD2, and PBRM1) (Table EV8)." (PMID 39592856, 2024). "The TCGA data show a differential expression trend that underscores the complexity and tumor-dependent nature of SETD2 dysregulation in cancer pathogenesis, highlighting the need for further research to elucidate its precise mechanisms and therapeutic implications across diverse tumor types." (PMID 38611113, 2024). "In addition, mutations in the tumour suppressors BAP1, PBRM1 and SETD2, which co-localise with VHL on chromosome 3p and are frequently disrupted in ccRCC, suppress ISGF3-mediated ISG expression." (PMID 39282259, 2024). "It remains to be determined whether SETD2 regulates tumor metabolism by interacting with these proteins and methylating them during PKD-ccRCC transition." (PMID 37989747, 2023). "Whether tumor cell‐intrinsic SETD2 alteration triggers TME reshaping, which might provide an alternative therapeutic strategy to treat patients with SETD2 deficiency, remains to be explored." (PMID 36453584, 2023). "SETD2 expression was also correlated with many features of tumor progression, including histological grade, clinical TNM stage, and invasion depth (T stage), which implied that low SETD2 expression was associated with high histological grade, clinical TNM stage, and T stage." (PMID 37604811, 2023). "The present study also provided mechanistic insight into the SETD2-dependent epigenetic regulation of ccRCC tumor suppression, indicating that SETD2 may serve as a therapeutic target for ccRCC treatment." (PMID 37604811, 2023). "Taken together, these studies provide evidence that SETD2 functions as a tumor suppressor in hematologic malignancies and that targeting the H3K36me3 demethylase may reverse chemotherapy resistance." (PMID 37359376, 2023). "As a tumor suppressor, SETD2 may serve as a biomarker to reduce drug resistance to targeted therapy and as a potential therapeutic target to promote individualized treatment and improve patient survival." (PMID 37025591, 2023). "Moreover, we found that knockdown of SETD2 increased lipid peroxidation and Fe2+ levels in tumor cells, thereby increasing the sensitivity of erastin, a ferroptosis inducer." (PMID 37604811, 2023).
tumor (continued). "In addition, SETD2 expression levels were negatively correlated with tumor stage, grade, and lymph node metastasis." (PMID 37359376, 2023). "Next, to explore whether the protumoral function of neutrophils in Setd2‐deficient tumors was dependent on CD8+ T cells, we injected a neutralizing antibody against Ly6G and/or CD8 into tumor‐bearing mice." (PMID 36453584, 2023). "Our results indicate that this model (BPS-TA) induces low numbers of somatic mutations in Bap1 and Pbrm1 (but not in Setd2), known tumor suppressor genes in human ccRCC." (PMID 37217526, 2023). "We note that neoplasia occurred in both SETD2-1740 and non-SETD2-1740 patient groups." (PMID 37166351, 2023). "Here, our approaches integrating a genetically engineered mouse model, RNA-Seq, and ATAC-Seq have established an epigenetic tumor suppressor model of SETD2 that lays the foundation for developing mechanism-based therapeutic strategies for SETD2-deficient cancers." (PMID 36810256, 2023). "SETD2 was significantly differentially underexpressed in tumor tissues compared to normal tissues." (PMID 37604811, 2023). "SETD2 is a tumor suppressor that is frequently inactivated in several cancer types." (PMID 36899051, 2023). "Therefore, tumor metastasis accompanied by metabolic alterations and further metabolic pathways analysis of SETD2 inactivated in ccRCC will have the potential to discover new therapeutics for precision medicine." (PMID 37025591, 2023). "The tumor-suppressive function of SETD2 is observed in various hematopoietic malignancies." (PMID 38036730, 2023). "SETD2 is a tumor suppressor in renal primary tubular epithelial cells (PTECs)." (PMID 37025591, 2023). "We also noted that two of 10 cases with a SETD2-NDD had developed a neoplasm." (PMID 37166351, 2023). "Moreover, Setd2 quantitatively ranks at the apex of all major tumor suppressors for its ability to suppress KRAS-driven cell proliferation." (PMID 36899051, 2023). "FECH expression was also correlated with many features of tumor progression, including histological grade, clinical TNM stage, and invasion depth (T stage), which implied that, similar to SETD2, low expression of FECH was associated with high histological grade, clinical TNM stage, and T stage." (PMID 37604811, 2023). "In human cancer, SETD2 has been shown to play a tumor-suppressor role." (PMID 35328487, 2022). "In addition to pre-mRNA splicing, SETD2’s function in mRNA polyadenylation and transcription termination has also been suggested to have tumor suppressive effects." (PMID 35661267, 2022). "Our study warrants further investigation into the molecular mechanism of translation regulation by SETD2, as well as studies to determine whether this function contributes to tumor development in SETD2 mutant or KDM4A-overexpressing cancers." (PMID 36052643, 2022). "Mutation of the histone H3 lysine 36 histone (H3K36) methyltransferase gene SETD2 may produce dysfunction in corresponding tumour tissue proteins, leading to tumorigenesis, progression, chemotherapy resistance, and unfavourable prognosis." (PMID 36510186, 2022). "In this group of patients, mutations in IDH2 (n = 3), KRAS (n =3), KIT (n = 3), and SETD2 (n = 1) were identified at low AF (median, 0.86%; range, 0.68 to 2.9%), though the corresponding mutation in the primary tumor was not known." (PMID 35273917, 2022). "Collectively, these studies indicate that (bi-allelic) SETD2 loss is a relatively late event in ccRCC development and is likely involved in tumor progression rather than initiation." (PMID 35661267, 2022). "Additional driver mutations in PBRM1, SETD2, and BAP1 may occur, and the number of driver events is significantly associated with tumor stage, grade, and presence of necrosis." (PMID 35463327, 2022).
tumor (continued). "SETD2 is a tumour suppressor leading to trimethylation of H3K36me3, which is a repressive mark." (PMID 35409426, 2022). "In addition to mRNA processing, SETD2 has tumor suppressor functions through its role in DNA repair (HR and MMR) and promoting chromosome segregation during mitosis (by catalyzing α-TubK40me3)." (PMID 35661267, 2022). "Overall, The SETD2 positive rate in tumor cells was lower than that in normal epithelial cells (15.2 vs. 20.2%, p = 0.2), but higher than that in immune cells, including T/NK cells (10.7%, p < 0.0001), B cells (8.4%, p < 0.0001), and myeloid cells (12.1%, p < 0.0001)." (PMID 36035179, 2022). "Colony formation assays indicated attenuated tumor proliferation after SETD2 knockdown." (PMID 36035179, 2022). "Multiple distinct mutations of SETD2, PTEN, and KDM5C genes were found within a single tumor." (PMID 34885018, 2021). "Our data revealed that, compared with SETD2 nonmutant patients, SETD2 mutant patients had higher tumor mutation burden and microsatellite instability." (PMID 34127768, 2021). "As a tumour suppressor, SETD2 has been extensively studied in cancers of different tissues." (PMID 33949020, 2021). "SETD2 is a regulator of various cellular processes such as RNA splicing, DNA repair, DNA methylation and histone modification, and is considered a tumor suppressor in unrelated tumor types." (PMID 33768452, 2021). "Furthermore, evidence of parallel evolution was demonstrated for multiple tumour suppressor genes (SETD2, PTEN, KDM5C), suggesting selective pressures drive inactivation of the same gene multiple times within a single tumour." (PMID 34459009, 2021). "Importantly, SETD2 and BAP1 mutations displayed lower allelic burdens than coexisting VHL mutations, suggesting that these mutations are acquired at later times during tumor development." (PMID 32751108, 2020). "In addition to EZH2 and SETD2, KMTs such as G9a, MLL, DOT1L and NSD1 are associated with tumor development and progression." (PMID 32859239, 2020). "Also, SCUBE2 mRNA and protein were prominently upregulated in tumor tissues of the circ_SETD2 group compared to that in the vector group." (PMID 33336052, 2020). "Taken together, SETD2 may be a regulator of tumor suppressor and can be used as a novel prognostic biomarker and therapeutic target." (PMID 32231741, 2020). "Besides, the expression level of SETD2 is significantly linked to tumor size, TNM stage, and lymph node metastasis, and down-regulated SETD2 expression is significantly associated with lower overall survival and lower 5-year survival in GC patients." (PMID 32231741, 2020). "SETD2 is a histone methyltransferase acting as a tumor suppressor by maintaining genome stability." (PMID 31867841, 2020). "Furthermore, circ_SETD2 expression was overtly elevated and miR-155-5p expression was markedly reduced in tumor tissues of the circ_SETD2 group when compared to the vector group." (PMID 33336052, 2020). "The remainder of the primary tumor was well-differentiated and SETD2-wt." (PMID 32674319, 2020). "Moreover, circ_SETD2 introduction curbed tumor growth in vivo and repressed cell cycle progression, proliferation, migration, and invasion, and facilitated apoptosis of BC cells in vitro." (PMID 33336052, 2020). "Mutation of SETD2 gene or its functional loss causes dysfunction of downstream signaling pathways, including wnt signaling pathway, PGC1α metabolic pathway and PI3K-mTOR signaling pathway, and such dysfunction is related to tumor occurrence." (PMID 32231741, 2020).
tumor (continued). "As the presence of KMT2D and SETD2 mutations were consistent in TNBC, we next explored if KMT2D and SETD2 mutational signatures were associated with detrimental prognosis in this specific tumor subtype." (PMID 30990809, 2019). "It would be interesting to see whether targeting H3K36me3 by SetD2 inhibitors selectively affects tumor cell survival in Lynch colorectal carcinoma." (PMID 31029155, 2019). "SETD2 SET domain played a critical effect on affecting tumor stage of ccRCC patients." (PMID 30755832, 2019). "This prompted us to examine whether the remaining major tumor suppressors in ccRCC, SETD2 and BAP1, also regulate ISGF3 in VHL-/-ccRCC cells." (PMID 30355451, 2018). "3p loss was subclonal in five tumors: one harboring a VHL mutation (K252), one VHL methylation (K070), one tumor that was VHL wild-type but SETD2 muttant (K427), and two with no mutations in any of the 3p genes (K169, K446)." (PMID 29656894, 2018). "One of the reasons that this could be such an interesting preventative opportunity is that the region of 3p loss invariably encompasses all four tumor suppressor genes of VHL, PBRM1, BAP1, and SETD2, and hence spans at least 40 Mb." (PMID 29656891, 2018). "SETD2 functions as a tumor suppressor in cancer progression." (PMID 30150556, 2018). "The relevance of these SETD2 functions to tumor suppression in ccRCC remains to be elucidated." (PMID 30355451, 2018). "Intra-tumor heterogeneity shows on one hand the presence of different phenotypes within the tumor (mTOR mutation) or, on the other, heterogeneous mutation sites in the same genes (SETD2, KDM5 and PTEN), indicating a phenotype convergence in the evolution of the tumor." (PMID 29491834, 2018). "Importantly, novel molecular markers were found:MAML3 (mastermind-like protein 3) fusions,SETD2 (SET domain containing 2) orATRX somatic mutations, and WNT-related expression subtype, which comprise the tumours withMAML3 fusion tumours." (PMID 29333259, 2017). "This bi-allelic inactivation of SETD2 was the first clue that the gene might be a tumor suppressor gene." (PMID 27191891, 2016). "SETD2 or BAP1 mutation alone did not discern tumour subsets with significantly different clinical outcomes in this uRCC cohort." (PMID 27713405, 2016). "SETD2 was found to be the most significantly recurrently mutated gene (MutSigCV P value=2.5 × 10−15 and a false discovery rate=4.8 × 10−11), observed in 86% (13/15) of EATL-II tumours with 20 distinctive mutations." (PMID 27600764, 2016). "Now that it is evident that SETD2-inactivation can be an important factor in tumor development and progression, especially in ccRCC, understanding the SETD2-inactivation-related pathways may offer new targets for therapy." (PMID 27191891, 2016). "Taking into account the cases of the WES cohort and the additional eight cases with targeted sequencing, interestingly, the two tumours with no alterations in SETD2 (case 13 and case 6) both harboured concurrent mutations in JAK1 and JAK3." (PMID 27600764, 2016). "The tumour suppressor gene SETD2 encoding a non-redundant H3K36-specific trimethyltransferase is altered in 14/15 cases (93%), mainly by loss-of-function mutations and/or loss of the corresponding locus (3p21.31)." (PMID 27600764, 2016). "Gene mutations (KDM5C and SETD2) that were highly correlated with ccRCC tumor size were not significantly correlated with survival (data not shown)." (PMID 26848523, 2016). "Independent of tumor type, a 200 CpG hypermethylation signature was established, demonstrating that loss of SETD2 alters the DNA methylome." (PMID 26646321, 2016). "Concerning the prognostic significance of BAP1, PBRM1 and SETD2 mutational status, BAP1 loss correlates with high Fuhrman nuclear grade and mTORC1 activation, higher tumor stage, and worst overall survival, while PBRM1 mutations seem to identify a favorable group of ccRCC." (PMID 26452128, 2015). "The SETD2 gene has been shown to play a tumour suppressor role in human cancer." (PMID 26172293, 2015).